IL6 (interleukin 6)
Diseases named in the same sentence as IL6 in open-access papers (continued):
Sharing a sentence is not in itself a finding about the gene and the disease.
psoriasis (continued). "IL-6 is highly expressed in active psoriatic plaques in patients with psoriasis compared to non-lesional biopsies." (PMID 40722824, 2025). "Elevated levels of CRP and IL-6 have been found to precede the onset of T2DM and CVD, suggesting that inflammatory dermatoses like psoriasis and LP may serve as early markers for cardiometabolic screening and intervention." (PMID 40870891, 2025). "While its role in psoriasis and obesity remains unexplored, NTBF strains have shown anti-inflammatory effects in vitro and in vivo, notably through modulation of cytokines such as IL-10, IL-1β, and IL-6, and downregulation of the NF-κB pathway." (PMID 41226468, 2025). "The acylated derivatives of luteolin inhibit imiquimod-induced psoriasis lesions in mice by down-regulating the expressions of TNF-α and IL-6 in the mouse skin tissue, increasing the contents of superoxide dismutase (SOD) and glutathione (GSH), and reducing the content of malondialdehyde (MDA)." (PMID 40144571, 2025). "Notably, HIF1A, IL-6, TNF, and IFNG were co-modulated by more than four BPs, indicating their central role in the mechanism of action of SHTLS in psoriasis treatment." (PMID 40507893, 2025). "The treatment targeting IL-6 or P-STAT3 could effectively inhibit the infiltration of neutrophils in the spleen and skin, thereby alleviating the progression of psoriasis." (PMID 40890773, 2025). "The principal receptors of psoriasis treatment are NF-κB, TNF-α, and interleukin IL-6." (PMID 38712377, 2025). "A previous study showed that patients with OSA have higher levels of IL-6 and TNF-α, which are also found in patients with psoriasis and treatment of OSA patients who had refractory psoriasis with continuous positive airway pressure (CPAP) has been shown to reduce psoriasis severity." (PMID 40232659, 2025). "In cellular models, Etoposide demonstrated promising therapeutic effects by significantly downregulating the expression of psoriasis-related keratinocytes marker genes (KRT6, KRT16) and CD-related inflammatory cytokines (IL6, IL8, TNF-α), highlighting its potential in treating psoriasis and CD." (PMID 40406126, 2025). "The authors can also conclude that although IL-6 is not the most important mediator of the inflammatory pathway in the skin environment, it is an interesting candidate biomarker for predicting psoriasis systemic treatment response." (PMID 37634972, 2024). "These dietary approaches can decrease levels of interleukin-6 (IL-6), vascular cell adhesion molecule-1 (VCAM-1), intercellular adhesion molecule-1 (ICAM-1), and low-density lipoprotein (LDL) in patients with psoriasis, thereby suppressing skin inflammation and abnormal keratinization." (PMID 39507900, 2024). "In mice with hyperlipidemic serum, increased IL-6 production by CD1b + DCs and IL-17A secretion by HJ1 T cells were observed, indicating that the potential link between hyperlipidemia and psoriasis might lie in self-lipid-reactive T cells." (PMID 38347543, 2024). "Studies have shown an elevated level of IL-6 in both RhA and psoriasis patients whilst in IBD there is not a significant elevation of IL-6." (PMID 39641040, 2024). "As obesity and psoriasis represent chronic inflammatory states, many recent studies have focused on the complicated role of visceral fat, which releases a number of pro-inflammatory cytokines such as TNF-α, IL-1, IL-6, and IL-8." (PMID 38473723, 2024). "When C3bot was added apically to the skin model, IL-6 abundance was reduced, but no further effects on the psoriasis-like phenotype of the epidermis were observed." (PMID 37707681, 2024). "Although IL-6 is not the most important mediator of the inflammatory pathway in the skin environment, it is an interesting biomarker candidate for predicting psoriasis treatment response." (PMID 37634972, 2024).
psoriasis (continued). "In the present study, LCAA-PSF was found to effectively slow down the inflammatory cytokine secretion of IMQ-induced psoriasis, including the expression of IL-23, IL-17A, TNF-α, and IL-6 in the serum and the expression of IL-17, Ki67, CK5/6 and VEGF in the affected skin area." (PMID 39062965, 2024). "Additionally, the gene expression of IL-6, IL-1b, and IL-17 was investigated in the IMQ-induced psoriasis mice that were treated with anti-IL-17 aptamer." (PMID 39045230, 2024). "Daphnetin treatment inhibits the proliferation and inflammatory response of human HaCaT keratinocytes and ameliorates imiquimod (IMQ)-induced psoriasis-like skin injury in mice and attenuates the IMQ-induced upregulation of inflammatory cytokines, including IL-6, IL-23A, and IL-17A." (PMID 39544933, 2024). "IL-6 and IL-22 work synergistically with IL-17A as potent STAT3 activators in psoriasis." (PMID 38892253, 2024). "Notably, IL-6 and TNF-α levels are elevated in both psoriasis and SDs and have been proven to induce keratinocyte hyper-proliferation in psoriasis;." (PMID 39411067, 2024). "In imiquimod-induced psoriasis, PARP1 showed an anti-inflammatory action, and its PARP1−/− mice model in genetic deletion exacerbated symptoms by increasing the secretion of cytokines IL-6, IL-17, and IL-23." (PMID 37298466, 2023). "The transcriptional expressions of Cxcl1, Cxcl2, Il-1β, Il-1α, S100A8, S100A9, Il-6, and Vegf were significantly decreased in skin lesions of K14.Bsgfl/fl mice, indicating the proinflammatory role of the epidermal expression of CD147 in psoriasis." (PMID 37303600, 2023). "Psoriasis is a quintessential immune-mediated inflammatory disorder, marked by heightened levels of proinflammatory markers and cytokines, including, but not limited to, tumor necrosis factor (TNF)-α, IL-6, IL-17, IL-22, and IL-238,9." (PMID 38102220, 2023). "Skin tissue RT-PCR detection determined that the IMQ + PBS groups in all three psoriasis mouse models had significantly increased TNF-α, IL-1, IL-6, IL-12, IFN-α, IFN-β, IFN-γ, G-CSF, GM-CSF, IL-36α, IL-36β, and IL-36γ gene expression compared to the NC groups." (PMID 37160878, 2023). "The immune response in psoriasis is characterized by proliferation of Th1, Th17, and Th22 cells resulting in the production of the pro-inflammatory mediators interferon-γ, tumor necrosis factor (TNF)-α, interleukin (IL)-6, and IL-22." (PMID 37895330, 2023). "For obese psoriasis patients, a strong negative connection to adiponectin was observed when compared to the pro-inflammatory cytokine IL-6." (PMID 37047363, 2023). "Another study with 47 psoriasis patients, serum levels of IL-6, TNF-α and proinflammatory adipocytokines (leptin, resistin and visfatin) were higher in psoriasis patients and serum adiponectin (an anti-inflammatory cytokine) was lower in psoriasis patients relative to healthy controls." (PMID 37681925, 2023). "Furthermore, chemerin was found to activate NF-κB and stimulate the expression of the pro-inflammatory cytokines IL-8, IL-6, and TNF-α, which are crucial in psoriasis pathogenesis." (PMID 37047363, 2023). "The Th17 cells produce IL-6, IL-17, and TNF-α to mediate the inflammatory reaction in psoriasis." (PMID 37596509, 2023). "In psoriasis, high serum levels of HIF-1α showed a correlation with overexpression of IL-6." (PMID 36961533, 2023). "According to a study on the therapeutic role of Centipeda minima in psoriasis using an in vitro model of the disease, the effect of the Centipeda minima extract (CMX) on macrophages and keratin-forming cells treated with LPS, IL-6, or IFN-y was assessed." (PMID 38202691, 2023). "This happens for IL-6, IFN-γ, IL-22, and IL-21, all involved in psoriasis." (PMID 36901778, 2023). "Although IL-6 serum levels were also found to increase in obese rats treated with ADA, ADA has been shown to reduce IL-6 circulating levels in long-term treatment studies of patients with HS and psoriasis." (PMID 36839941, 2023).
psoriasis (continued). "Finally, mechanistic studies, including the blockage of the IL-6/TGF-β axis, would be required to depict the mechanism by which MSC alleviates the imiquimod-mediated psoriasis-like skin inflammation." (PMID 37373278, 2023). "Increased levels of IL-6 and TNF-α were observed in serum after psoriasis." (PMID 36982669, 2023). "The current work aimed to investigate the whole blood GLUT1 mRNA expression and serum PEDF, IL-6, fetuin-A, and PTX3 levels in psoriatic patients and tested their correlations with the severity of psoriasis using the psoriasis area and severity index (PASI) score." (PMID 38052851, 2023). "Although IL-6 plays a role in the maturation of Th17 cells, search of the literature and clinical trials in websites did not reveal psoriasis studies with anti-IL-6/IL-6 receptors and role on Tregs frequency and Th1/Tregs balance." (PMID 36901778, 2023). "Furthermore, they postulated that PCSK9 is connected with a higher atherosclerotic burden in psoriasis patients, and, using blood transcript analysis, they identified TNF, IL6, IL17A, and IL23 as PCSK9-related pathways." (PMID 37234169, 2023). "Real-time PCR results further confirmed that the mRNA levels of psoriasis-related factors keratin-17, integrin β1, and CXCL9, as well as the mRNA levels of inflammation-related factors IL-1β, IL-6, TNF-α and iNOS, were strongly inhibited in skin of Mincleflox/flox/Lyz-cre+/+ mice." (PMID 37117184, 2023). "The activation of the α7nAChR by its agonist PNU-282987 significantly inhibited the STAT3 signaling activation induced by IL-6 and IL-22, indicating that PNU-282987 had the potential to inhibit Th17-mediated inflammation in the skin and alleviate the psoriasis symptom." (PMID 35351863, 2022). "Our results showed that ELE significantly inhibits the expression of IL1A, IL1B, IL6, and IL8 in M5-stimulated keratinocytes, demonstrating that ELE suppresses the inflammatory responses of psoriasis keratinocytes by attenuating the expression of various interleukins." (PMID 36467042, 2022). "Analysis of the genome-wide transcription pattern of monocytes revealed IL6 as the top gene induced by S100 alarmin stimulation via interaction with TLR4, and targeted deletion of S100A9 ameliorated inflammation in a murine psoriasis model." (PMID 35543413, 2022). "Since our findings show that PNU-282987, a selective α7nAChR agonist, can improve the lesioned skin of IMQ-stimulated mice as well as IL-6/IL-22 induced HaCaT cells, we next investigate the effect of Methyllycaconitine citrate (METH), a selective α7nAChR antagonist, on IMQ-induced psoriasis." (PMID 35351863, 2022). "In the pathogenesis of psoriasis, IL-17 interacts with keratinocytes to promote the production of antimicrobial peptides, proinflammatory cytokines and chemokines (IL-1β, TNF-α, IL-6, IL-17C, CXCL1, CXCL3, CXCL5, CXCL8 [IL-8] and CCL20) and proliferative cytokines (IL-19)." (PMID 35514987, 2022). "The levels of IL-6, TNFα and IL-17 were significantly reduced as compared to the vehicle group, suggesting SHR168442 suppressed the production of Th17 pathway related cytokines in IL-23-induced Psoriasis-like skin inflammation mice." (PMID 33911101, 2021). "This may result from elevated proinflammatory cytokines in psoriasis-TNF, IL-17, IL-1 and IL-6, which are known to inhibit melanogenesis and specifically PKA, MITF, TYR and DCT." (PMID 34884858, 2021). "Several pro-angiogenic cytokines, such as IL-6, TNF-α, and IL-17, are up-regulated in psoriatic lesions, which may contribute to the increase in blood vessel formation in psoriasis patients." (PMID 33995368, 2021). "IL-37 inhibits the IL-1β, IL-6, and TNF cytokines—which play fundamental roles in psoriatic inflammation—but it can also suppress some chemokines, such as CCL2, which is also important in psoriasis and rheumatic diseases." (PMID 34360845, 2021). "IL-24 is a member of the IL-20 family induced by IL-6, TNF, and IL-1β in psoriasis." (PMID 34054833, 2021).
psoriasis (continued). "Psoriasis is a disease with a proinflammatory base, in which an increased expression of leptin, tumor necrosis factor alpha (TNF-α), interleukin (IL) IL-12/23, IL-6, is observed." (PMID 33562571, 2021). "When psoriasis persists or worsens, IFN-α and VEGF released by activated PDCs and keratinocytes provoke myeloid DCs (MDCs) that express proinflammatory cytokines including TNF-α, IL-1β, IL-6, and IL-23." (PMID 34281197, 2021). "We transfected si-ATG5 and pc-ATG5 into HaCaT cells and detected the expression of IL-6 and IL-1β to investigate whether the ATG5 gene could be used as a therapeutic target for the management of psoriasis." (PMID 34113484, 2021). "In psoriasis, IL-1 stimulates the synthesis of additional cytokines and the expression of cytokeratin 6 (CK6), a marker of hyperproliferative and activated keratinocytes, whereas IL-6 stimulates T-cell proliferation and keratinocyte hyperproliferation." (PMID 34679744, 2021). "Furthermore, the ELISA data showed that the pro-inflammatory mediators including IL-6, IL-17A, IL-23, IL-24, and TNF dramatically increased in psoriasis-like mice intervened by shLuc." (PMID 34638757, 2021). "In addition, expression of inflammation-related cytokines including IL-17, IL-6, and TNF-α upregulated by application of IMQ was decreased by ANO1 inhibition, showing that psoriasis-like inflammation is alleviated by inhibition of ANO1." (PMID 34281197, 2021). "Drug targets identified by us that are already in use for the different IMIDs include drugs that target IL1B, IL6, TYK2, and JAK2.IL1B was present in the common cell-gene network of AS, CD, psoriasis, RA, and UC, indicating a similar mechanism between these diseases." (PMID 34108969, 2021). "Therefore, we used RT-PCR to assess the mRNA levels of inflammatory cytokines, such as IL-6, TNF-α, IL-17A, and IL-17F, in skin tissues of mice with IMQ-induced psoriasis." (PMID 33995368, 2021). "IL-1 family member IL-37 can interact with the IL-18 receptor, and IL-37 overexpression in human keratinocytes inhibits the production of CXCL8, IL-6, and S100A7, suggesting that IL-37 may play an immunosuppressive role in psoriasis pathogenesis." (PMID 33055429, 2020). "Cases of psoriasis-like dermatitis exhibited significantly higher serum IL-6 levels compared to those of IL-6 in cases without any irAEs (P < 0.0001 by Mann–Whiney U test)." (PMID 33060784, 2020). "In addition, TNF-α and IL-6 expression were downregulated in unstimulated peritoneal macrophages from CX3CR1−/− mice, consistent with our previous report on imiquimod-induced psoriasis-like skin inflammation model in CX3CR1−/− mice." (PMID 33036460, 2020). "It correlates with IL-6 and TNF-α in the blood of patients with psoriasis." (PMID 32899610, 2020). "We determined the mRNA expression levels of several inflammatory cytokines that are important in psoriasis (TNF-α, IL-23p19, IL-17A, IL-22, IFN-α, IL-1β, IL-6, and IL-10) and a chemokine that promotes the migration of neutrophils (CXCL2) using quantitative real-time PCR." (PMID 32752186, 2020). "Smits and colleagues established psoriasis and atopic dermatitis models using N/TERT epidermal skin by adding Th1/Th17 (TNF-α, IL-6, IL-1α, IL-17, and IL-22) cytokines and Th2 (IL-4 and IL-13) cytokines, respectively, during the final stage of the skin maturation." (PMID 32509598, 2020). "In fact, several cytokines that are known to be key players in the pathogenesis of psoriasis, such as tumor necrosis factor- (TNF-) alpha, interleukin- (IL-) 2, IL-6, and IL-17, are also found to be at an increased concentration in the aqueous humor of patients with uveitis." (PMID 32724820, 2020). "It has been widely used in patients with rheumatoid arthritis and psoriasis, significantly reducing serum levels of IL‐6, TNF‐α and IFN‐γ.9, 10 In a phase III clinical trial in patients with moderate‐to‐severe psoriasis conducted in India, itolizumab was effective and well tolerated." (PMID 33304584, 2020).
psoriasis (continued). "In order to validate this phenomenon, we analyzed the serum levels of IL-6 in eight cases of psoriasis-like dermatitis, and 19 cases without any irAEs." (PMID 33060784, 2020). "Oral administration of genistein in psoriasis patients for 8 weeks impaired the transcription of genes overexpressed in psoriasis, CXCL10, IL-6, STAT3, NFKB1, CCL4 while stimulated the transcription of gene repressed in psoriasis, IL-1RN in peripheral blood cells or lesional skin." (PMID 32751360, 2020). "Dysregulated Th17 cells and IL-17 synthesis in the skin, synovial space and endothelium promote synthesis of pro-inflammatory cytokines namely IL-1β, TNF and IL-6 and neutrophil chemoattractants such as IL-8, CCL20 and CCL2 as observed in psoriasis and psoriatic arthritis." (PMID 33737877, 2020). "In addition to IL-6, a transient increase in IL-23 followed by IL-17A production was observed in the IMQ-induced psoriasis model." (PMID 31659208, 2019). "Some features of CD11b deficiency like enhanced activation of NFκB and other TLR-dependent pathways, Th-17 cells expansion, higher activity of DCs and production of some pro-inflammatory cytokines, e.g. IL-1β, IL-6, IL-12, IL-23, and TNF-α, are observed in psoriasis." (PMID 31211819, 2019). "Regarding IL-6, in patients with geographic tongue and psoriasis cases the staining was stronger than in patients with geographic tongue without psoriasis cases." (PMID 31789253, 2019). "Results of the study confirmed the superior activity of naringin/sericin combination compared with each compound alone on down-regulation of the pro-inflammatory cytokines including IL-6, IL-12p40, IL-23 and TNF-α related to early inflammation mechanisms of psoriasis pathogenesis." (PMID 31291937, 2019). "Fatty tissue, as a source of a wide range of proinflammatory mediators (e.g., IL-6), may contribute to development of systemic inflammation and impact the AGE accumulation in patients with psoriasis." (PMID 30363704, 2018). "In addition, TNF- α, IL-1β, IL-6, and INF-γ have been found to increase the production of C3 from the liver and probably from adipose tissue in psoriasis patients." (PMID 29416693, 2018). "Moreover, followingstimulation of STAT3 phosphorylation by IL-6/IL-22, the ensuing signaling pathwayleads to overexpression of VEGF during psoriasis." (PMID 29630472, 2018). "There is an abundance of evidence to suggest that proinflammatory cytokines (IL-6) and chemokines (IL-8, MDC) produced by keratinocytes may be responsible for skin inflammatory diseases including psoriasis." (PMID 28464025, 2017). "IL-6, IL-8, and CXCL-1 play active roles in the development of psoriasis." (PMID 28217129, 2017). "To further investigate and characterize the exact role of IL-6 signaling in myelomonocytic cells during experimental psoriasis, we generated mice lacking the IL-6 receptor alpha specifically in myelomonocytic cells (IL-6RαΔmyel)." (PMID 26999594, 2016). "Our study shows that classical IL-6 signaling in myelomonocytic cells does not play an essential role for disease development of IMQ-induced psoriasis-like skin disease." (PMID 26999594, 2016). "Most well known psoriasis related genes activated in non-lesional skin are IL6, IL22, IL36A, IL36G, IL19, IL20, S100A7 and S100A12." (PMID 25897967, 2015). "Importantly, the synergistic effects of IL-17 and TNF-alpha are capable of further upregulating IL-6 in psoriasis lesional skin; hence, selective targeting of either IL-17 or TNF-alpha exerts additional beneficial effects by indirectly reducing IL-6 levels." (PMID 25126586, 2014). "Our data thus confirm the involvement of Th22 cells in psoriasis, as recently suggested by other authors which also found increased serum levels of IL-22 in the presence of anincrease of IL-6 and in the absence of IL-17 increments." (PMID 25136144, 2014).